ATRX (ATRX chromatin remodeler)
Diseases named in the same sentence as ATRX in open-access papers (continued):
Sharing a sentence is not in itself a finding about the gene and the disease.
metastatic disease (continued). "ATRX, a gene located on the X chromosome encoding a chromatin remodeling protein belonging to the SWI/SNF protein family, showed uniformly strong expression across all cases by IHC, including Case 24 where ATRX heterozygous deletion was identified exclusively in the metastatic tumor." (PMID 41317331, 2026). "In our study, heterozygous ATRX copy number loss was exclusively identified in the metastatic tumor of Case 24, notably without corresponding protein expression loss." (PMID 41317331, 2026). "Extrapolating this finding, the heterozygous loss of ATRX in Case 24 may abrogate XCI, which might explain the retained expression of ATRX protein in the metastatic tumor." (PMID 41317331, 2026). "ATRX/DAXX loss/mutations and ALT positivity are associated with a more aggressive phenotype, such as a larger tumor size, high grade, advanced stage, chromosomal instability, metastatic disease, and poor survival." (PMID 36556070, 2022). "In metastatic disease, DAXX/ATRX loss seems to be associated with longer survival." (PMID 35326628, 2022). "PCC is a tumor type known to have better clinical outcomes, however our PCC patients developed metastatic disease and ultimately died, thus suggesting that the presence of ATRX variants and perhaps a large tumor size, rather than the primary location, contributed to adverse outcomes." (PMID 39351526, 2024). "Two cases with metastatic disease had an unknown ATRX status." (PMID 37629169, 2023). "A TERT promoter mutation was found in eight of eleven cases with metastatic disease, with no ATRX loss in six cases and unknown ATRX status in two cases." (PMID 37629169, 2023). "Only one CM case with metastatic disease revealed neither a TERT promoter mutation nor ATRX loss." (PMID 37629169, 2023). "Two cases with metastatic disease without a TERT promoter mutation did show ATRX loss." (PMID 37629169, 2023). "Subsequently, in order to determine whether ATRX loss has prognostic value in CM we evaluated ATRX status in CM cases with recurrent disease versus CM cases without recurrent disease as well as CM cases with metastatic disease versus CM cases without the development of metastatic disease." (PMID 37629169, 2023). "Ten primary tumours from patients with metastatic disease did not have TERT/ATRX-alterations, but the late acquisition of TERT/ATRX alterations and presence in metastatic cells could not be excluded given that the metastatic tissue was not sequenced." (PMID 38978571, 2024).
brain tumors (18 papers, 2014 to 2024). "This makes sense as only GBM 4 had a mutated IDH gene and ATRX mutations in brain tumours are frequently detected with IDH mutations." (PMID 32041307, 2020). "Although less prevalent overall in gliomas compared to the mutually exclusive TERT promoter mutations, ATRX mutations and ALT are frequent in specific molecular subgroups of sporadic brain tumors, particularly IDH mutant astrocytomas." (PMID 35740680, 2022). "Endogenous proteins were followed in the human oligodendrocytic MO3.13 cell model because ATRX is highly expressed in brain tissue and is often deregulated in brain tumours." (PMID 34780483, 2021). "The 2016 WHO classification of diffuse LGGs heavily weighs molecular mutations classifying primary brain tumors with particular importance assigned to IDH mutation, 1p/19q co-deletion, ATRX mutation, TERT mutations, and MGMT methylation." (PMID 32111869, 2020). "We also reported the presence of somatic mutations in the genes encoding H3.3 and ATRX, as these mutations are frequently found in ALT paediatric brain tumors." (PMID 32331249, 2020). "Based on histomolecular characteristics described in the Materials and methods section, we selected, according to the WHO 2016 classification of brain tumors, 60 IDH-mutant anaplastic astrocytomas (AA) and 44 IDH-mutant GBM that all exhibited loss of ATRX." (PMID 31706351, 2019). "Some of the frequently mutated genes have been rarely reported in brain tumors according to the COSMIC database: EPH2B (67% vs 1.11%), DICER1 (67 vs 1.25%), KMT2B (67% vs 1.46%), ATRX (67% vs 13.95%) as well as several muscular genes (DMD, MYO10, MYO9B, MYH6) (P < .00001, Fischer exact test)." (PMID 39233831, 2024). "ATRX mutations and ALT are associated with specific molecular subgroups of sporadic brain tumors." (PMID 35740680, 2022).
breast carcinoma (18 papers, 1999 to 2025). "For example, BAP1 loss or germline mutations have been linked to prolonged survival in malignant pleural mesothelioma, and BAP1 overexpression appears to promote basal type breast cancers and myeloid neoplasms harboring certain ATRX mutations." (PMID 31903168, 2019). "Previously ATRX pathogenetic or unknown variants have been reported in 0–0.9% of breast cancers, depending on the biological subtype." (PMID 36085291, 2022). "Characteristics of breast cancer patients and their ATRX expression level." (PMID 38126976, 2023). "Except for ATRX, all of them showed hyper-methylation in breast cancer." (PMID 28424414, 2017). "The result showed that U50A consistently downregulates SMC5, ATRX, CENPE, and CENPF, indicating a widespread phenomenon that these genes are downstream targets of U50A in breast cancer." (PMID 34944924, 2021). "For example, target genes of BAP1 deubiquitination include mutant ATRX in myeloid neoplasms and Krüppel-like factor 5 (KLF5) in basal-like breast cancers, which both become stabilized by BAP1 and consequently accelerate tumor growth." (PMID 31903168, 2019). "R/M breast cancer more frequently harbored alterations in BRCA2, ATRX, and ATM (p<0.05)." (PMID 40182039, 2025).
leiomyosarcoma (16 papers, 2017 to 2025). An uncommon, aggressive malignant smooth muscle neoplasm, usually occurring in post-menopausal women. "The ATRX gene, a tumor suppressor and chromatin remodeler, demonstrated the highest mutation frequency (10.1%), particularly among leiomyosarcoma, consistent with other reports." (PMID 40563612, 2025). "ATRX alteration is associated with the down-expression of genes linked to differentiation in leiomyosarcomas, and to immunity in an additional cohort of 60 poorly differentiated pleomorphic sarcomas." (PMID 33946962, 2021). "The degree of cell differentiation may be crucial for the loss of ATRX to confer advantages to the precursor leiomyosarcoma cell." (PMID 33946962, 2021). "Our study noted a similar DDR alteration rate in leiomyosarcoma (24%), with the majority of alterations in ATRX, which plays a role in HRR." (PMID 40563612, 2025). "A characteristic feature of uterine leiomyosarcoma is the frequent involvement of the ATRX and DAXX genes, which regulate chromatin remodeling and telomere maintenance." (PMID 41463261, 2025). "In fact, only about 50% of ALT+ leiomyosarcomas and pleomorphic liposarcomas are also ATRX deficient; at the same time ALT+ appears to be highly correlated with ATRX loss in angiosarcomas and dedifferentiated liposarcomas." (PMID 30871494, 2019). "Similarly, in ATRX altered uterus leiomyosarcoma, RAD51B alterations exerted an additive effect on telomeric elongation (2226 TRPM in double-altered vs 1449 in RAD51B altered only and 812 in ATRX altered only)." (PMID 37709802, 2023). "Since there is a correlation between ATRX/DAXX loss and an ALT+ phenotype in ULMS, these characteristics could potentially be used as markers to better discern STUMP entities as either uterine leiomyomas or leiomyosarcomas." (PMID 34069193, 2021). "Based on TCGA, we determined that 3 of the most common subtypes of soft tissue sarcoma, undifferentiated pleomorphic sarcoma, myofibrosarcoma, and leiomyosarcoma (STS cohort), had recurrent alterations in the ATRX gene, which occurred in 24% of samples." (PMID 37200088, 2023).
oligoastrocytoma (14 papers, 2012 to 2025). A WHO grade II tumor composed of a conspicuous mixture of two distinct neoplastic cell types morphologically resembling the tumor cells in oligodendroglioma and diffuse astrocytoma. "In the study by Sahm and colleagues investigating 43 mixed oligoastrocytomas, 1p/19q codeletion and ATRX loss were mutually exclusive in all but one case, suggesting parting with the diagnosis of oligoastrocytoma." (PMID 27556304, 2016). "Among 38 cases of mixed oligoastrocytomas with analyzable data of ATRX expression and TERTp mutation, the two biomarkers showed mutual exclusivity in all but one case." (PMID 27556304, 2016). "Only very rare reports describe tumours as “true” oligoastrocytomas, consisting of histologically and genetically discrete astrocytic (IDH-mutant, ATRX-mutant, 1p/19q-intact) and oligodendroglial (IDH-mutant, ATRX-wildtype, and 1p/19q-codeleted) mixed populations of tumour cells." (PMID 33477674, 2021).
cognitive deficits (12 papers, 2008 to 2026). "Mutations in ATRX result in moderate to profound cognitive deficits, facial dysmorphisms, as well as skeletal and urogenital abnormalities, among other symptoms." (PMID 18842153, 2008). "Mutations in the ATRX gene result in profound cognitive deficits, facial dysmorphisms, as well as skeletal and urogenital abnormalities." (PMID 18842153, 2008). "Further investigation is warranted to elucidate how these mutations impact the subnuclear localization of ATRX, the pathological consequences of aberrant ATRX localization, and the differential effects of mutations across various regions on the development of intellectual impairment." (PMID 39479502, 2024). "Of note, IDH-1 and ATRX mutations are also associated with cognitive deficits." (PMID 35148403, 2022). "It is likely that inactivation of ATRX in postmitotic neurons, following neurogenesis and lamination, will help define a role for ATRX target genes in altered synaptic activity and/or synaptic plasticity underlying cognitive impairment." (PMID 32849845, 2020). "Specific repression of ERVs has been shown to rescue cognitive deficits, suggesting that retroelement activation may contribute to neuroinflammation and cognitive deficits in ATRX miKO mice." (PMID 40938932, 2025). "The eclectic properties of the ATRX protein do not make it intuitively obvious how an aberration of these functions can result in a neurodevelopment disorder with cognitive deficits." (PMID 32849845, 2020). "Previous research indicated that the absence of ATRX leads to cognitive impairment and promotion of cellular senescence, further highlighting the significance of exploring the interplay between TERRA, ATRX, and aging-related cellular processes in the brain and neuronal tissues." (PMID 40637232, 2025).
neuroendocrine tumors (12 papers, 2018 to 2026). "ATRX was expressed in 66.7% of neuroendocrine tumor tissues, and 3 (33.3%) patients showed a loss of expression." (PMID 30627226, 2018). "MEN1, DAX, and ATRX mutations are associated with well-differentiated neuroendocrine tumors (NETs)." (PMID 37373998, 2023). "Similar to the neuroendocrine tumors (NETs) of other sites, NEBCs also host mutations in chromatin remodeling genes including ARID1A and ATRX." (PMID 32414120, 2020). "ATRX gene changes were associated with abnormal alternative telomere lengthening and poor prognosis in pancreatic non-functioning neuroendocrine tumors." (PMID 38884081, 2024). "Furthermore, we observe distinct drivers which are enriched in somatic aberrations in pancreatic (MEN1, ATRX, DAXX, DMD and CREBBP) and midgut-derived neuroendocrine tumors (CDKN1B)." (PMID 34326338, 2021).
colorectal cancer (11 papers, 2015 to 2025). A primary or metastatic malignant neoplasm that affects the colon or rectum. "These higher mutation frequencies of PRKDC and ATRX from the right-sided tumors than the left-sided may be related to the more frequent observation of MSI-high cases from the colorectal cancer patients with right-sided tumors." (PMID 35003350, 2021). "Here we investigated the function of the chromatin-remodelling helicase ATRX in colorectal cancer (CRC)." (PMID 40468074, 2025). "Here we identify the chromatin-remodelling enzyme ATRX as a key regulator of colonic lineage fidelity and metastasis in colorectal cancer." (PMID 40468074, 2025). "ATRX-mutant colorectal cancer cells show reduced ability to form heterochromatic foci compared to wildtype controls." (PMID 34763709, 2021). "It has been recently shown that ATRX-mutant colorectal cancer cells are resistant to therapy-induced senescence, due to an inability of ATRX-mutant cells to form the requisite heterochromatic foci." (PMID 34763709, 2021). "While ATRX loss-of-function is found in various tumors, overexpression of ATRX has been reported in colorectal cancer cell lines." (PMID 35087762, 2021). "This excess CENP-A partners with histone H3, and associates with transcriptionally coupled chaperones ATRX and DAXX in colorectal cancer cell lines." (PMID 25788983, 2015). "Collectively, our study defines the epigenetic maintenance of colonic epithelial identity by ATRX and HNF4A as suppressors of lineage plasticity and metastasis in colorectal cancer." (PMID 40468074, 2025). "The chromatin-remodelling enzyme ATRX and the transcription factor HNF4A are identified as pivotal regulators of colonic epithelial identity, with roles in metastasis in colorectal cancer." (PMID 40468074, 2025).
insulinomas (11 papers, 2017 to 2025). "Groups sequencing larger cohorts including insulinomas have reported ATRX mutations in insulinoma very rarely." (PMID 36835815, 2023). "This patient’s tumor is the first malignant insulinoma to our knowledge to possess simultaneous mutations in ATRX, ROS1, and KMT2A." (PMID 36835815, 2023). "With regards to the most common genes that mutate in pancreatic neuroendocrine neoplasms (panNENs) (MEN1, ATRX and DAXX) only loss of ATRX was detected in insulinoma sample." (PMID 34737724, 2021). "YY1 was shown to be recurrently mutated in insulinomas, while mutations in ATRX/DAXX/MEN1 are very uncommon." (PMID 32512761, 2020). "Of the two subtype A insulinoma patients, one relapsed after a period of 10 years and died of her disease, while the other had a large tumor that had acquired an ATRX mutation, which is supposed to be a later stage alteration." (PMID 32512761, 2020). "All insulinomas (n = 34) with tumor tissue present in the TMAs had retained ATRX expression, only one case had heterogenic DAXX loss (also ALT positive)." (PMID 32103422, 2020). "Rarely, metastatic insulinomas show ARX positivity with concurrent loss of DAXX/ATRX and ALT activation, suggesting a distinct tumorigenic mechanism in malignant insulinomas similar to nonfunctional pancreatic NETs through transdifferentiation from α cell tumors." (PMID 40026252, 2025). "Affirming these reports, the L2027R ATRX mutation noted in our patient affords additional credence to this suggestion that chromosomal instability from DAXX/ATRX mutations may represent an important genomic basis for the aggressive behavior of malignant insulinoma." (PMID 36835815, 2023). "Amplification of the first exon of ATRX in insulinoma sample that we noticed on CNVPanelizer was confirmed with a statistical significance of p-value < 0.01." (PMID 34737724, 2021). "Visualizing the results of CNVPanelizer on genome coordinates (hg19) we have noticed that in the insulinoma sample the data for the first exon of ATRX was higher (shown in red rectangle) than the reference values, whereas the downstream exons were lower." (PMID 34737724, 2021). "While the vast majority of β-like PanNETs expressed PDX1 and insulin, the two malignant (N1 and/or M1) insulinomas of our cohort, showed one intermediate-ADM (DAXX/ATRX mutated) and one α-like (DAXX/ATRX wild-type) methylation signatures." (PMID 33288854, 2020). "It was posited from these results that ATRX and DAXX mutations, which are typically more characteristic of NF-pNETs, may be more common in malignant insulinomas than in their less aggressive counterparts." (PMID 36835815, 2023). "Copy number alterations involving FOXL2, IRS2, CEBPA and ATRX genes were observed in insulinoma as well as in micro-tumors samples, suggesting that alterations of these genes may promote malignization in the β-cells population." (PMID 34737724, 2021). "As expected, the majority of insulinomas expressed PDX1, except one malignant and one DAXX/ATRX mutated insulinomas, which showed nuclear positivity for ARX but not for PDX1." (PMID 33288854, 2020). "A recent large whole-genome sequencing study definitively established that insulinomas and non-functional PanNETs have distinct genetic underpinnings, and recurrent copy number variations together with ATRX and DAXX mutations are a characteristic feature of non-functional PanNETs." (PMID 32103422, 2020). "Retention of ATRX/DAXX protein expression in one of the insulinomas with ALT may be explained by non-truncating mutations, translocations, or other underlying mutations causing the ALT phenotype." (PMID 32103422, 2020). "In insulinomas, mutations in MEN1, ATRX and DAXX that are often mutated in all PNETs occur in no more than 10 percent: 3%, 8% and 3%, respectively." (PMID 34737724, 2021).